EGFR (epidermal growth factor receptor)
Diseases named in the same sentence as EGFR in open-access papers (continued):
Sharing a sentence is not in itself a finding about the gene and the disease.
interstitial lung disease (continued). "Of note, the expression of driver mutations in EGFR, BRAF, and KRAS G12C in patients with NSCLC with concurrent interstitial lung disease is vastly different compared to those patients with NSCLC without Interstitial Lung Disease." (PMID 39062713, 2024). "In line with other EGFR inhibitors, abivertinib potentially poses heightened concerns regarding severe adverse reactions such as interstitial lung disease and hepatotoxicity." (PMID 38611728, 2024). "ECOG > 2, pre-existing interstitial lung disease (ILD), squamous cell histology, combination therapies of ICI and EGFR TKIs are discussed as potential risk factors for CIP." (PMID 35804997, 2022). "A common aspect between SARS-CoV-2 and the EGFR TKIs is that they promote interstitial lung disease, having a high similarity of symptoms and radiological showings." (PMID 34063231, 2021). "EGFR-TKI-related adverse events (AEs) are usually tolerable and manageable, although serious AEs, including lung injury (specifically, interstitial lung disease (ILD), causing 58% of EGFR-TKI treatment-related deaths), occur infrequently." (PMID 33466795, 2021). "EGFR TKIs are known to have the side effect of promoting interstitial lung disease in the patients receiving these drugs." (PMID 34063231, 2021). "The currently reported risk factors for EGFR‐TKI‐related interstitial lung disease (ILD) include age, being male, a previous history of interstitial lung disease, and complicated heart disease." (PMID 33438350, 2021). "Pulmonary toxicity is important from the point of view of eventual lung surgery because development of interstitial lung disease (ILD) being a consequence of administration of EGFR-TKIs significantly impairs physiological fitness." (PMID 34830123, 2021). "As with other EGFR TKIs, prompt management of adverse events is needed in the Japanese population, to reduce serious events and outcomes, including interstitial lung disease." (PMID 30953238, 2019). "A previous clinical study has identified risk factors of EGFR TKI-induced pneumonitis including old age, smoking history, pre-existing interstitial lung disease, and poor performance status." (PMID 31426531, 2019). "Interstitial lung disease (ILD) is a serious side-effect of epidermal growth factor receptor (EGFR)-tyrosine kinase inhibitor (TKI) treatment." (PMID 26497205, 2015). "However, EGFR-TKI-induced interstitial lung disease (ILD) is a recognized and severe adverse reaction that can be fatal." (PMID 42051259, 2026). "The toxicity profile of lazertinib has been noted to include manageable side effects typical of EGFR inhibitors, such as rash and diarrhea, without the severe cardiotoxicity or interstitial lung disease often associated with this drug class." (PMID 38611728, 2024). "Compared to neoadjuvant chemotherapy, the use of EGFR inhibitors has fewer severe respiratory adverse events (including pneumonitis and interstitial lung disease), which could limit the use of neoadjuvant therapy." (PMID 39081712, 2024). "However, EGFR-TKI-induced interstitial lung disease (ILD), a well-known adverse effect, can seriously affect the treatment outcome." (PMID 38895622, 2024). "Interstitial lung disease (ILD) was a severe adverse response to EGFR TKIs." (PMID 38001917, 2023). "Besides, EGFR has dual pro-fibrotic and anti-fibrotic effect, and cancer patients treated with EGFR tyrosine kinase inhibitors-monoclonal antibody present an elevated incidence of interstitial lung disease." (PMID 35754492, 2022). "The prevalence and severity of other AEs, including interstitial lung disease (ILD) and liver function impairments that have been considered idiosyncratic and are usually not linked to the effectiveness of EGFR inhibition, are correlated with the potency of EGFR inhibition." (PMID 35330404, 2022). "In addition, a series of data have reported that drug-induced interstitial lung disease (ILD) is seen in NSCLC patients receiving EGFR-TKIs." (PMID 35747920, 2022).
interstitial lung disease (continued). "Although a higher proportion of interstitial lung diseases was reported with the combination of osimertinib and durvalumab, the current evidence on the treatment-related adverse events (trAEs) of EGFR-TKI and ICI remains limited to pneumonitis and the use of osimertinib." (PMID 35565285, 2022). "Interstitial lung disease (ILD) is 1 of the fatal side effects of EGFR-TKIs." (PMID 33546082, 2021). "One patient discontinued treatment on day 8 because of drug‐ induced interstitial lung disease and showed EGFR exon 21 point mutation in ctDNA without available tumor tissue (Group A)." (PMID 33270375, 2021). "Interstitial lung disease (ILD) is considered as a major safety concern for EGFR-TKIs." (PMID 26599904, 2015). "In a different study, it was shown that, in response to combined gefitinib (EGFR inhibitor) and LPS treatment, mice expressing ectopic Fra-1 develop interstitial lung disease, accompanied by diminished levels of TNF-α, MIP-1α and MIP-2 when compared with wild-type mice." (PMID 22911824, 2012). "A significantly higher number of patients in the PDL1-positive group developed interstitial lung disease (ILD) after EGFR-TKI therapy than those in the PDL1-negative group." (PMID 39156250, 2024). "This study investigated the safety and efficacy of epidermal growth factor receptor (EGFR)-tyrosine kinase inhibitor (TKI) re-administration after recovery from EGFR-TKI-induced interstitial lung disease (ILD)." (PMID 38265672, 2024). "For example, osimertinib, the 3rd generation of EGFR TKI targeting EGFR T790M; L858R (TL) mutations, is a cysteine-directed covalent drug that less-specifically binds to cysteine-rich tissues, including lung and spleen causing interstitial lung disease, diarrhoea, and hyperglycaemia." (PMID 36810913, 2023). "Rash, paronychia, diarrhea, stomatitis, liver dysfunction and (interstitial lung disease, ILD) are frequently observed in patients treated with EGFR-TKI." (PMID 30827323, 2019). "Similar to fatal pneumonitis, interstitial lung disease (ILD) have also been represented in advanced NSCLC patients treated with EGFR-TKIs (gefıtinib: 3.5%; erlotinib: about 1.6%-4.5%) and with chemotherapy (docetaxel: 4.6%; gemcitabine: < 1%)." (PMID 28938671, 2017). "Interstitial lung disease (ILD) events have been reported in Japanese non-small-cell lung cancer (NSCLC) patients receiving EGFR tyrosine kinase inhibitors." (PMID 21799770, 2011). "A 60‐year‐old woman with stage IVB EGFR‐mutated lung adenocarcinoma and prior brain metastases was initially treated with osimertinib but discontinued therapy after developing CTCAE grade 2 interstitial lung disease (ILD)." (PMID 41537168, 2026). "Osimertinib’s signal for interstitial lung disease (ROR025 = 13) was second only to Gefitinib and significantly higher compared to other EGFR-TKIs." (PMID 40135231, 2025). "However, notable toxicities related to EGFR TKIs includes acneiform rash, diarrhea, paronychia, and interstitial lung disease (ILD)/pneumonitis which can lead to fatal outcomes." (PMID 38919534, 2024). "However, EGFR-TKI-induced interstitial lung disease (ILD) can occur as a critical, potentially lethal, adverse event." (PMID 38265672, 2024). "However, a significantly higher incidence of drug-induced interstitial lung disease (ILD) was detected with osimertinib than with the first-generation EGFR-TKIs (p = 0.008)." (PMID 37179737, 2023). "For osimertinib, the latest generation of anti-EGFR TKIs, in the pivotal study FLAURA, 4% of patients in the osimertinib arm developed interstitial lung disease compared to 2% of patients in the standard EGFR-TKI arm (gefitinib or erlotinib)." (PMID 33801385, 2021). "Furthermore, in a subgroup analysis of epidermal growth factor receptor (EGFR)–tyrosine kinase inhibitor (TKI)-induced interstitial lung disease (ILD), we observed seven candidate SNVs that were possibly associated with ILD (P < 0.00001)." (PMID 31584970, 2019).
interstitial lung disease (continued). "However, the combination of EGFR-TKI and anti-PD-1/L1 is discontinued due to high toxicity and adverse effects (AEs), especially immune pneumonia and interstitial lung disease." (PMID 39004699, 2024). "Interstitial lung disease (ILD) is a rare and fatal adverse event induced by EGFR-TKIs." (PMID 37089959, 2023). "Interstitial lung disease is considered to be the most serious and fatal TKI-related ADR because the inhibition of EGFR signaling may damage the repair capability of lung cells and worsen pulmonary injury resulting in death." (PMID 36505840, 2022). "For example, epidermal growth factor receptor (EGFR) and TKR promote interstitial lung diseases." (PMID 34830303, 2021). "However, interstitial lung disease (ILD), potentially fatal, may develop in certain patients during EGFR-TKI therapy." (PMID 40949116, 2025). "Severe hepatic dysfunction can be managed by switching to another EGFR-TKI, whereas lung injury (also known as interstitial lung disease (ILD)) often leads to the discontinuation of EGFR-TKI treatment in the affected patients." (PMID 33466795, 2021). "None of the patients demonstrated interstitial lung disease in response to EGFR-TKI." (PMID 21194487, 2011). "Although it is a concern that ICI treatment after EGFR‐TKI treatment frequently induces interstitial lung disease (ILD), there was no ILD in this study." (PMID 34904383, 2022). "However, another trial targeting Asian patients with EGFR-WT non-squamous NSCLC was prematurely terminated due to the increased incidence of interstitial lung disease in patient group treated with erlotinib and tivantinib, although preliminary data revealed that the PFS was longer in that group." (PMID 28619066, 2017). "Notably, both Gefitinib and Afatinib had an interstitial lung disease (ILD) incidence rate of 1%, while no reports were made for the other EGFR-TKIs." (PMID 40135231, 2025). "Inclusion: advanced NSCLC, EGFR wild type and EML4-ALK fusion-negative, ECOG 0–1.Exclusion: symptomatic central nervous system metastases, use of corticosteroids,* interstitial lung disease or active infection." (PMID 38886117, 2024). "However, due to the high incidence of interstitial lung disease (ILD), this study arm was stopped prematurely, as was the phase 3 CAURAL trial (NCT02454933) assessing osimertinib plus durvalumab vs osimertinib in second-line EGFR-mut NSCLC patients." (PMID 31463163, 2019). "Attempts to combine EGFR TKIs with ICIs were not successful, as the TATTON study, which involved an EGFR TKI and durvalumab, was discontinued due to toxicity primarily due to interstitial lung disease (ILD)." (PMID 38107063, 2023).
pulmonary fibrosis (79 papers, 2011 to 2026). Chronic progressive interstitial lung disorder characterized by the replacement of the lung tissue by connective tissue, leading to progressive dyspnea, respiratory failure, or right heart failure. "On the other hand, aberrant EGFR activation has been implicated in several human diseases, including pulmonary fibrosis, cancer progression, cardiovascular diseases, and Alzheimer’s disease." (PMID 39118068, 2024). "Another recent study showed that epidermic growth factor receptor (EGFR) positivity and pulmonary fibrosis are associated with increased D-dimer levels, CRP levels, and prolonged ICU stay." (PMID 37893011, 2023). "Transforming growth factor (TGF)-α, a ligand for the epidermal growth factor receptor, has also been implicated in the pathogenesis of pulmonary fibrosis." (PMID 37047672, 2023). "Sulfated polysaccharides such as fucoidan can inhibit or interfere with the activation and expression of epidermal growth factor receptor (EGFR) as the main pathway causing pulmonary fibrosis." (PMID 35462942, 2022). "Hyperactive EGFR signaling can then instigate onset and progression of pulmonary fibrosis associated with severe infections caused by respiratory viruses including SARS-associated coronavirus (SARS-CoV)." (PMID 35083168, 2021). "The available data are contradictory given that anti-EGFR TKIs can cause pulmonary fibrosis in humans while preventing pulmonary fibrosis in mice, so there can be several ways of explaining the difference." (PMID 34063231, 2021). "The disregulated expression of the epidermal growth factor receptor, a protein involved in cell signaling pathways, has been associated with overproduction of mucous, progression or lung fibrosis, and excessive airway proliferation." (PMID 32218378, 2020). "Abnormalities in EGFR pathways cause abnormal EGFR signalling and are associated with cancer, lung fibrosis, and numerous airway diseases." (PMID 33396348, 2020). "Conversely, mice deficient in TGFα that lack normal EGFR signalling or that are treated with EGFR pathway inhibitors exhibit resistance to bleomycin-induced lung fibrosis." (PMID 30050057, 2019). "EGFR activation is associated with fibroproliferative processes in human lung disease and animal models of pulmonary fibrosis." (PMID 28961023, 2017). "To clarify the underlying mechanism of why metformin attenuates EGFR-TKI-induced exacerbation of pulmonary fibrosis in vivo, we next analyzed the TGF-β signaling pathway and EMT in harvested lung tissues." (PMID 26497205, 2015). "EGFR mRNA levels were positively associated with indicators of lung fibrosis (type 1 collagen mRNA levels) and negatively correlated with functional prognostic parameters." (PMID 23841084, 2013). "Univariate analyses revealed that preexisting pulmonary fibrosis at baseline was the only risk factor for EGFR-TKIs induced ILD." (PMID 21791074, 2011). "Univariate analyses revealed that only preexisting pulmonary fibrosis (odds ratio, 4.683; 95% CI, 1.741-12.042; p = 0.003) was a significant risk factor for the development of EGFR-TKIs induced ILD." (PMID 21791074, 2011). "Univariate analyses revealed that only preexisting pulmonary fibrosis was a significant risk factor for the development of EGFR-TKIs induced ILD (p = 0.003)." (PMID 21791074, 2011). "In this study, univariate analysis revealed that preexisting pulmonary fibrosis was the only risk factor for developing EGFR-TKIs induced ILD." (PMID 21791074, 2011). "EGFR mutations were identified in 43 (35.2%) of 122 patients with normal lungs, 8 (13.6%) of 59 with emphysema, and 1 (5.9%) of 17 with pulmonary fibrosis." (PMID 22191026, 2011). "In this study, one patient with pulmonary fibrosis and an EGFR mutation treated with gefitinib developed fatal ILD." (PMID 22191026, 2011). "EGFR has been implicated in the pathogenesis of pulmonary fibrosis." (PMID 32850151, 2020).
pulmonary fibrosis (continued). "The EGFR pathway has been implicated in lung fibrosis through studies in which transgenic mice that constitutively express TGFα in epithelial cells develop progressive lung fibrosis." (PMID 30050057, 2019). "Therefore, it is necessary to study underlying mechanisms for the development of pulmonary fibrosis induced by EGFR-TKI and potential approaches to attenuate it." (PMID 26497205, 2015). "The presence of EGFR mutations in patients with pulmonary fibrosis was rare in this study." (PMID 22191026, 2011). "Only one (5.9%) of 17 patients with pulmonary fibrosis had an EGFR mutation." (PMID 22191026, 2011). "Risk factors, such as tobacco exposure, pre-existing lung fibrosis, chronic obstructive pulmonary disease, and poor performance status, indicate that lung inflammatory circumstances may worsen with EGFR-TKI treatment because of impaired epithelial healing of lung injuries." (PMID 33466795, 2021). "Experimental results confirmed that MOL000332 (n-coumaroyltyramine) significantly mitigated pulmonary fibrosis by suppressing the protein expression levels of EGFR, HIF1A, and GSK3B." (PMID 41847136, 2026). "All EGFR-TKIs except dacomitinib had significant signals for lung infiltration, pulmonary toxicity, pulmonary fibrosis, and alveolitis." (PMID 40949116, 2025). "Given our findings, the Hif-1α-EGFR signaling pathway appears to be crucial for APD's regulation of ferroptosis in pulmonary fibrosis." (PMID 38584671, 2024). "Immunohistochemistry showed distinct brown deposits, indicative of EGFR protein presence, in the tracheal epithelium of pulmonary fibrosis mice." (PMID 38584671, 2024). "Further analysis using the Kyoto Encyclopedia of Genes and Genomes suggested a crucial role for the Hif-1α-EGFR signaling pathway in ferroptosis and pulmonary fibrosis." (PMID 38584671, 2024). "EGF, a canonical ligand of EGFR, which mediates an important signaling axis for the development of lung fibrosis, was also found to be significantly increased in these supernatants." (PMID 38976646, 2024). "HB-EGF binds to and activates epidermal growth factor receptor (EGFR), a key regulator of lung fibrosis after SARS-CoV-2 infection." (PMID 38397975, 2024). "Specifically, the mechanism involving the inhibition of Hif-1α-EGFR and its relation to ferroptosis in pulmonary fibrosis needs more exploration." (PMID 38584671, 2024). "Of these six master regulators, three master regulators are found to be associated with pulmonary fibrosis (ERBB2, EGFR and FGFR2) and one with inflammation (FYN)." (PMID 37206915, 2023). "The EGFR-specific small molecule inhibitor gefitinib also exacerbated bleomycin-induced pulmonary fibrosis in mice." (PMID 36307516, 2022). "EGFR phosphorylation (p-EGFR) was reported to promote pulmonary fibrosis by activating downstream signaling pathways in fibroblasts." (PMID 35551173, 2022). "This is further supported by similar findings in SARS-CoV-2 infected patients, whereby EGFR was again found to be a regulator of pulmonary fibrosis." (PMID 36203591, 2022). "EGFR inhibition was reported to prevent skin, liver, and kidney fibrosis, but exacerbated lung fibrosis." (PMID 36490328, 2022). "EGFR also plays a deleterious role in other pulmonary conditions, such as asthma, viral infection, and pulmonary fibrosis." (PMID 36193076, 2022). "It was found that the severity of EGFR involvement and pulmonary fibrosis in patients who died from COVID-19 pneumonia correlated with CRP levels." (PMID 36353282, 2022). "Within the lungs, EGFR plays an important role in the regeneration of epithelial cells to augment lung fibrosis." (PMID 34638265, 2021). "Even with a bleomycin- or naphthalene-induced lung fibrosis/injury model, the best animal model should use EGFR-TKI alone to induce pulmonary injury or fibrosis." (PMID 33466795, 2021).